REXO2 (RNA exonuclease 2)
Description:
3'-to-5'exoribonuclease that preferentially degrades DNA and RNA oligonucleotides composed of only two nucleotides. Binds and degrades longer oligonucleotides with a lower affinity. Plays dual roles in mitochondria, scavenging nanoRNAs (small RNA oligonucleotides of <5 nucleotides) that are produced by the degradosome and clearing short RNAs that are generated by RNA processing. Essential for correct initiation of mitochondrial transcription, degrading mitochondrial RNA dinucleotides to prevent RNA-primed transcription at non-canonical sites in the mitochondrial genome. Essential for embryonic development (By similarity). [Isoform 3]: 3'-to-5'exoribonuclease that preferentially degrades DNA and RNA oligonucleotides composed of only two nucleotides.
Synonyms: SFN; CGI-114; DKFZP566E144; REX2; RFN
Tractability: PROTAC: ubiquitination databases record sites on it; its protein half-life has been measured.
Gene: Protein-coding gene on chromosome 11 (114,439,386 to 114,450,296, forward strand). Ensembl gene ENSG00000076043.
Subcellular location: Mitochondrion intermembrane space; Mitochondrion matrix; Mitochondrion; Cytoplasm; Nucleus; Cytoplasm (Isoform 3)
Subcellular location (Human Protein Atlas): Mitochondria; Focal adhesion sites; Nucleoli
Pathways (Reactome):
Metabolism of RNA: Mitochondrial RNA degradation
Gene Ontology:
Molecular function: 3'-5' exonuclease activity; 3'-5'-DNA exonuclease activity; 3'-5'-RNA exonuclease activity; magnesium ion binding; nucleic acid binding
Biological process: mitochondrial RNA surveillance; nucleobase-containing compound metabolic process; nucleotide metabolic process; RNA metabolic process
Cellular component: cytoplasm; mitochondrial intermembrane space; mitochondrial matrix; mitochondrion; nucleus
Genetic constraint (gnomAD): Loss-of-function variants: 12 observed, 14.8 expected, observed/expected ratio (o/e) 0.81, 90% interval 0.52 to 1.31. The upper end of that interval is the gene's LOEUF score, 1.31, which puts it in group 5 of 6, group 1 being the genes least tolerant of losing a copy. Missense variants: 180 observed, 185.41 expected, observed/expected ratio (o/e) 0.97, 90% interval 0.86 to 1.1. Synonymous variants: 80 observed, 69.76 expected, observed/expected ratio (o/e) 1.15, 90% interval 0.96 to 1.38.
Homologues: Orthologues: chimpanzee REXO2 (100% identical), macaque REXO2 (99% identical), dog REXO2 (98% identical), guinea pig REXO2 (97% identical), rabbit REXO2 (97% identical), pig REXO2 (97% identical), mouse Rexo2 (94% identical), rat Rexo2 (94% identical), tropical clawed frog rexo2 (72% identical), zebrafish smfn (68% identical), Drosophila melanogaster CG10214 (43% identical), Caenorhabditis elegans C08B6.8 (37% identical).
Diseases named in the same sentence as REXO2 in open-access papers:
REXO2 is named in the same sentence as 17 diseases in open-access papers, as found by Europe PMC text mining. Sharing a sentence is not in itself a finding about the gene and the disease. The quoted sentences say what the papers report.
breast carcinoma (3 papers, 2019 to 2025). "Notably, among those genetic alteration events whose loss enhances CDK4/6i sensitivity, CDK6, CCND3, CCNE1 and E2F3 were frequently amplified in the genomes of breast cancer patients, whereas among the genes whose loss promotes resistance, RB1, REXO2, PPP2R2A and STT3A were mainly depleted." (PMID 34508104, 2021).
COVID-19 (3 papers, 2021 to 2023). A disease caused by infection with severe acute respiratory syndrome coronavirus 2. "Understanding the biology and functional significance of the four obtained genes (TRMT2A, EXOSC5, REXO2, and MESD) provides insights into the molecular processes associated with disease severity in COVID-19." (PMID 37347079, 2023).
glioma (2 papers, 2021 to 2024). A benign or malignant brain and spinal cord tumor that arises from glial cells (astrocytes, oligodendrocytes, ependymal cells). "REXO2 hyper-methylation was associated with the favorable prognosis of LGG or glioma." (PMID 34088969, 2021). "Further evidence of this is observed in the heightened expression levels of RUNX1 and its downstream target, REXO2, in isocitrate dehydrogenase wild-type low-grade gliomas, indicative of a poor prognosis." (PMID 39309442, 2024). "Glioma patients with RUNX1 or REXO2 hypo-methylation had worse clinical outcomes than LGG patients with RUNX1 or REXO2 hyper-methylation in TCGA dataset." (PMID 34088969, 2021). "We found that REXO2 highly expressed glioma had lower overall survival than REXO2 lowly expressed glioma patients in TCGA (P < 0.0001) and CGGA (P < 0.0001) datasets." (PMID 34088969, 2021). "RUNX1 and REXO2 were further hypo-methylated in grade IV glioma (GBM) patients in TCGA dataset." (PMID 34088969, 2021). "Moreover, REXO2 expression and methylation were associated with IDH mutation and the clinical outcomes of LGG or glioma patients." (PMID 34088969, 2021). "Furthermore, REXO2 was further over-expressed in grade IV glioma (GBM) patients in TCGA (P = 3.9E−37) and CGGA (P = 1.2E−06) datasets." (PMID 34088969, 2021). "Furthermore, RUNX1 and REXO2 were correlated with the worse prognosis of LGG or glioma." (PMID 34088969, 2021).
pheochromocytoma (1 paper, 2020). "REXO2 has a 3′-to-5′ exonuclease activity, and its dysregulation leads to tumorigenesis of pheochromocytoma by disturbing the DNA replication, recombination, and repair processes." (PMID 33193734, 2020).
sarcoma (1 paper, 2022). A usually aggressive malignant neoplasm of the soft tissue or bone. "Upregulated mtRBP genes included Fus (fused in sarcoma), Puf (pumillo and FBF 60 homolog), Rexo2 (RNA exonuclease 2), and RNasel and RNase4 (ribonucleases)." (PMID 35754828, 2022).
tumor (6 papers, 2018 to 2025). "At last, we showed that, age, tumor grade and REXO2 expression were independent prognostic factors in IDH wild type LGG." (PMID 34088969, 2021). "Furthermore, REXO2 expression was a prognostic marker independent IDH alteration, age and tumor grade, suggested that REXO2 was a good prognostic maker to predict the clinical outcomes of LGG." (PMID 34088969, 2021). "REXO2, MSI1, and ESRP2 had high expression levels in tumors compared with normal tissues, while CTU1, MAEL, and YBX2 were undetermined in both tumor and normal tissues." (PMID 33193734, 2020). "In CGGA dataset, tumor grade (P = 0.014) was an independent prognostic marker in IDH wild type LGG patients, while, age and REXO2 expression were not independent prognostic markers (P = 0.213 and P = 0.595, respectively)." (PMID 34088969, 2021).
REXO2 also shares sentences with these, for which no sentence is quoted: melanoma (3 papers); cancer (2); colorectal cancer (1); epilepsy (1); glioblastoma (1); infection (1); lung adenocarcinoma (1); malaria (1); metabolic disease (1); pancreatic cancer (1); teratocarcinoma (1).